CTXN1 (cortexin 1)
Description:
May mediate extracellular or intracellular signaling of cortical neurons during forebrain development.
Synonyms: CTXN; FLJ25968
Tractability: Antibody: UniProt predicts a signal peptide or a membrane-spanning region; the Human Protein Atlas places it where antibodies can reach. PROTAC: ubiquitination databases record sites on it.
Gene: Protein-coding gene on chromosome 19 (7,924,491 to 7,926,135, reverse strand). Ensembl gene ENSG00000178531.
Subcellular location: Membrane
Subcellular location (Human Protein Atlas): Nucleoplasm; Cell Junctions; Plasma membrane
Gene Ontology:
Cellular component: membrane
Genetic constraint (gnomAD): Loss-of-function variants: 4 observed, 2.44 expected, observed/expected ratio (o/e) 1.64, 90% interval 0.68 to 1.94. That is too few expected variants to judge how well the gene tolerates losing a copy. Missense variants: 111 observed, 73.25 expected, observed/expected ratio (o/e) 1.52, 90% interval 1.3 to 1.77. Synonymous variants: 67 observed, 37.16 expected, observed/expected ratio (o/e) 1.8, 90% interval 1.46 to 1.97.
Homologues: Orthologues: chimpanzee CTXN1 (100% identical), macaque CTXN1 (100% identical), pig CTXN1 (100% identical), dog CTXN1 (99% identical), guinea pig CTXN1 (99% identical), rat Ctxn1 (98% identical), mouse Ctxn1 (96% identical), tropical clawed frog ctxn1 (68% identical), zebrafish ctxn1 (63% identical), zebrafish ctxn1 (54% identical). Paralogues in human: CTXN3 (43% identical), CTXN2 (41% identical).
Diseases named in the same sentence as CTXN1 in open-access papers:
CTXN1 is named in the same sentence as 4 diseases in open-access papers, as found by Europe PMC text mining. Sharing a sentence is not in itself a finding about the gene and the disease. The quoted sentences say what the papers report.
glioma (2 papers, 2023 to 2025). A benign or malignant brain and spinal cord tumor that arises from glial cells (astrocytes, oligodendrocytes, ependymal cells). "Knocking out CTXN1 in GL261 glioma cells in mice reduced tumor burden, improved survival rates, and enhanced infiltration of CD8+ T cells." (PMID 40977710, 2025). "ScRNA‐seq analysis, GSC models, and section‐paired patient samples collectively affirmed CTXN1 expression in gliomas." (PMID 38116063, 2023). "Among these genes, CTXN1, which is involved in neuronal signaling and cortical development, was overexpressed in gliomas with poor prognosis." (PMID 38116063, 2023). "To explore the functional role of CTXN1 in glioma progression and immune response, we manipulated its expression in GL261 cells by shRNA‐mediated knockdown (shCtxn1) or overexpression (oeCtxn1) and validated the effects by qRT‐PCR." (PMID 38116063, 2023). "Then, we also examined CD3+, CD8+ cells, and CTXN1 expression in glioma cases." (PMID 38116063, 2023). "Interestingly, glioma samples with diminished CTXN1 expression exhibited elevated levels of CD3+ and CD8+ T cells." (PMID 38116063, 2023).
glioblastoma (1 paper, 2023). The most malignant astrocytic tumor (WHO grade IV). "Single‐cell RNA sequencing analysis, along with investigations in a glioblastoma stem cell model and patient sample analysis, demonstrated the predominant localization of CTXN1 within tumor cores rather than peripheral regions." (PMID 38116063, 2023). "We also examined CTXN1 expression by patient samples, the glioblastoma stem cell (GSC) model (MES28) and scRNA‐seq (3505 cells), finding a negative correlation between CTXN1 and CD8+ T cell infiltration, as evidenced by Immunohistochemistry staining." (PMID 38116063, 2023).
lymph node metastasis (1 paper, 2025). "Transcriptomic profiling revealed a molecular signature (ALDH1A3, CTXN1, MGAT3, and TMEM163) of occult lateral lymph node metastasis, exhibiting strong robustness (AUC = 0.857)." (PMID 40977710, 2025).
tumor (2 papers, 2023 to 2025). "We confirmed the spatial distribution of CTXN1 in both paired patient samples and GSC mouse models, revealing lower CTXN1 expression in the peripheral tumor region compared with the tumor cores." (PMID 38116063, 2023). "Knockdown of Ctxn1 not only curtailed tumor growth but also improved survival in vivo, concomitant with an augmentation in CD8+ T‐cell infiltration." (PMID 38116063, 2023). "In vivo, Ctxn1 knockdown in GL261 cells led to decreased tumor burden and improved survival while increasing infiltration of CD8+ T cells." (PMID 38116063, 2023). "In subsets cluster of neoplasms, CTXN1 demonstrated predominant expression in tumor cores." (PMID 38116063, 2023). "Knocking down Ctxn1 in GL261 cells prolonged survival and reduced tumor weight in mice‐bearing tumors, while increasing the infiltration of CD8+ T cells within tumors." (PMID 38116063, 2023). "Ctxn1 knockdown in GL261 cells led to decreased tumor weight and prolonged survival time while increasing tumor CD8+ T cells infiltration." (PMID 38116063, 2023). "The Infiltration of CD8+ T cells is inversely correlated with CTXN1 expression in the tumor core rather than the periphery." (PMID 38116063, 2023).